CDKN2A (cyclin dependent kinase inhibitor 2A)
Diseases named in the same sentence as CDKN2A in open-access papers (continued):
Sharing a sentence is not in itself a finding about the gene and the disease.
melanoma (continued). "Finally, absence of CDKN2A mutation or large deletion does not rule out the possibility that epigenetic modification of either p16 or p14ARF could result in gene silencing that would contribute to melanoma." (PMID 18612309, 2008). "Analysis of Swedish patients with multiple primary melanomas and NST was negative for the CDKN2A founder mutation 113insArg, which usually explains all CDKN2A-associated familial melanoma in Sweden." (PMID 15928671, 2005). "In the present study, 42 Jewish, mainly Ashkenazi, melanoma families with (n=24) or without NST (n=18) were genotyped for germline sequence alterations in the CDKN2A/ARF and CDK4 genes." (PMID 15928671, 2005). "In conclusion, in the majority of Ashkenazi Jewish families with an inherited predisposition to melanoma with or without NST, CDKN2A/ARF and CDK4 loci are unlikely to be implicated in the predisposition to melanoma and the associated neural system tumours." (PMID 15928671, 2005). "When correlated with molecular data, MTAP loss showed 100% specificity and a positive predictive value of 100% for detecting CDKN2A homozygous deletion, but only 41% sensitivity, confirming that MTAP immunostaining alone lacks optimal sensitivity for detecting all CDKN2A-inactivated melanomas." (PMID 41596618, 2026). "However, the identification of a potentially POT1 PV in a family diagnosed with multiple early-onset melanomas underscores the need for continued genetic screening in hereditary melanoma cases, especially when CDKN2A, CDK4, and BAP1 aberrations are absent." (PMID 40851494, 2025). "However, CDKN2A, while widely studied in malignancies like melanoma and glioblastoma, has not yet been reported in the context of VS to our knowledge." (PMID 41231782, 2025). "The immune escape mechanism may be triggered by the modifications in the DNA methylation pattern, as in the case of melanoma, promoter methylation in the case of PTEN, CDKN2A or ARF was observed in several melanoma patients leading to poor prognostic and cell cycle dysregulation." (PMID 40427015, 2025). "Moreover, we constructed a miRNA–miRNA interaction network using the miRNet tool, revealing key regulatory genes in melanoma, including PLAG1, TGFBR2, CDKN2A, MAPK14 and MYC, which exhibited significant degrees and betweenness centrality in the network analysis." (PMID 39823244, 2025). "Finally, MGPT also led to the identification of SFs, such as two PVs in CDH1 and one PV in CDKN2A in BC patients without a personal/family history suggestive of hereditary diffuse gastric cancer or melanoma and pancreatic carcinoma syndrome, respectively." (PMID 40361347, 2025). "Previous studies have shown that alterations in CDKN2A expression are more frequent in OSCC than in other solid tumors such as pancreatic tumors, bladder cancer, renal cell carcinoma, non-small cell lung cancer, melanoma, glioma, gastroesophageal junction and gastric adenocarcinomas." (PMID 39590385, 2024). "Furthermore, in Italy, a pathogenic variant in high- or medium-penetrance genes was detected in only 9% of 273 Italian CDKN2A-negative melanoma cases." (PMID 39596909, 2024). "In addition, we acknowledge that methotrexate has not shown clinical efficacy in melanoma, and therefore other factors beyond p16/CDKN2A status are likely at play." (PMID 38626341, 2024). "A negative correlation between CDKN1A and CDKN2A was found, especially in primary melanoma." (PMID 38070141, 2023). "Therefore it is not a surprise that CDKN2A was reported to be the most common inactivated tumor suppressor gene in melanoma." (PMID 37626750, 2023).
melanoma (continued). "CDKN2A and either BRAF or NRAS (non-simultaneously) mutations may occur concurrently within one melanoma tumour, contributing to difficulty in ongoing and initial tumour treatment." (PMID 36614303, 2023). "However, previous GenoMEL studies of familial melanoma, involving histopathology review by multiple expert pathologists, did not identify spitzoid morphology in CDKN2A carrier and noncarrier familial melanomas." (PMID 36876055, 2023). "Moreover, we detected that PD-L1 expression was positively correlated with some cuproptosis-related genes (CDKN2A, FDX1, LIPT1, and MTF1), but negatively correlated with other cuproptosis-related genes (ATP7B, DLST, and PDHA1) in an analysis of 470 melanoma patients." (PMID 35837286, 2022). "Consequently, we performed whole exome sequencing (WES) of 10 probands from 5 different families (2 probands/family) who developed melanoma and had previously tested negative for CDKN2A and CDK4." (PMID 35085295, 2022). "Tumor suppressors and oncogenes with a demonstrated role in melanoma tumorigenesis and progression lay on regions that are recurrently aneuploid, including the oncogenes BRAF (7q34) and MYC (8q24) and the tumor suppressors BAP1 (3p21), CDKN2A (9p21) and PTEN (10q23)." (PMID 36276131, 2022). "Furthermore, in melanoma-prone families with pancreatic cancers, ATM variants were only observed in patients without germline CDKN2A mutations." (PMID 34573422, 2021). "Recently, it was reported that inactivation of Cdkn2a/p16ink4a gene by CRISPR/Cas9 significantly favored lung metastasis of mouse non-small cell lung carcinoma transplanted subcutaneously and artificial inactivation of CDKN2A gene initiates the invasion of human melanoma cells via BRN2 activation." (PMID 35004325, 2021). "Interestingly CDKN2A methylation was rarely detected in sporadic primary melanoma and has not been identified in melanocytic nevi." (PMID 33076392, 2020). "The observation of a melanocyte-like phenotype was supported by the fact that shRNA-Tsc2 + Cdkn2a sphere cells that were differentiated in neural-crest differentiation medium showed similar positive staining for CATHEPSIN K, PMEL, MITF and MART-1 to the B16F1 melanoma cell line." (PMID 29133867, 2017). "In contrast to CDKN2A, which is known to be lost in many melanomas, we did not observe significant changes in FOXM1 gene copy number, suggesting the FOXM1 increase may be due to elevated transcription." (PMID 26279295, 2016). "In addition to the known tumor suppressor genes CDKN2A and CDKN2B, it was suggested that other genes and loci in this region may also be involved in melanoma and cutaneous nevi development." (PMID 23209811, 2012). "Yet, the lack of mutations at the genes analysed in this series of melanoma families with NST is commensurate with data from other melanoma-NST families genotyped for mutations: in a family with melanoma and optic nerve glioma, no mutations were identified in the CDKN2A gene." (PMID 15928671, 2005). "In addition to targeted therapies, the absence of CDKN2A may impact the effectiveness of immunotherapy in melanoma." (PMID 38534309, 2024). "Additionally, individuals with CDKN2A PVs have an increased probability of multiple primary melanomas: one study reported a 23% incidence of second melanoma primary diagnosed within 5 years of the first, representing a 10-fold increase over that of melanoma patients without CDKN2A PVs." (PMID 35372037, 2022).
melanoma (continued). "In addition to that, some patients with germline CDKN2A PV may not undergo genetic testing, so clinicians may be unaware of this information when they start first line treatment for advanced melanoma." (PMID 34069952, 2021). "We investigated the IRAK-M DNA methylation profiles of patient samples and melanoma cell lines and found that reduced methylation within the promoter region of IRAK-M correlated with increased transcript levels, neither did they correlate with BRAF or NRAS mutation status, nor CDKN2A genotype." (PMID 32533049, 2020). "Further, we identified a variant of unknown functional significance in the 5’UTR of an FPC patient that we had never found in melanoma cases and we hypothesized that a subset of PC patients could harbor rare functional variants in the 5’UTR of CDKN2A gene as well." (PMID 29216274, 2017). "Detection of two high-risk MC1R variants in our identical twins in the absence of CDKN2A and CDK4 mutations highlights the contribution of low penetrance genes, such as MC1R, in melanoma susceptibility, although additional known or as yet unknown genetic risk factors might be involved." (PMID 22978401, 2012). "While other genes (e.g. CDKN2C, CDKN2A, MITF, BAP1, PTEN, ERBB4, and FGFR2, etc.)are mutated with some frequency in melanoma, no common recurring mutations in these genes are observed or the function of observed mutations are unknown; therefore these genes were not included in our screen." (PMID 22536370, 2012). "However, protein expression of CDKN2A by immunohistochemistry correlated well with gene dosage ratios as determined by MLPA in the majority of tumors investigated, and is consistent with the view that deletion remains the dominant method of CDKN2A silencing in primary melanoma." (PMID 20140953, 2010). "By reviewing literature, only one Singaporean case with germline 9p21.3 deletion involving CDKN2A, CDKN2B, and partial MTAP and ANRIL genes had no melanoma but squamous cell carcinoma in the head and neck." (PMID 40046620, 2025). "Although CDKN2A and CDK4 are the most commonly tested genes to date, no unique standard guidelines on which genes to include in familial melanoma genetic testing are currently available." (PMID 40869905, 2025). "CDKN2A was also enriched for non-duplication events (39/81, 48%) in BRAF-mutant cutaneous melanomas compared with the other genomic subtypes." (PMID 38758740, 2024). "Finally, molecular screening of CDKN2A, p14 (specific exon-1β) and CDK4 genes, which are involved in approximately 20–40% of large, high-risk families, performed both on the proband and on the cousin affected by melanoma (III.4), did not identify any pathogenetic sequence variant." (PMID 29346284, 2018). "A few melanoma‐prone families, with no linkage to CDKN2A, have been found to carry PVs in CDK4, thus having alterations affecting the same cellular mechanism as CDKN2A, since p16INK4a is a direct inhibitor of CDK4 function." (PMID 40072281, 2025). "Meanwhile, it was confirmed that in melanoma, CDKN1A and CDKN2A could not affect the miR-300 transcription and maturation process." (PMID 38070141, 2023). "Although the potential involvement of the CDKN2A and PTEN genes cannot be excluded, it does not directly explain the observed effect of UVB and tryptophan metabolites on the migration and invasiveness of melanoma SK-MEL-3 cells." (PMID 34299117, 2021). "However, Cdkn2a−/−, Tyr-HRAS melanomas do not metastasize and other cancers, predominantly B cell lymphomas and soft-tissue sarcomas, also occur." (PMID 27429258, 2013).
melanoma (continued). "Moreover, a recent in vitro study showed that simultaneous knockdown of BRAF and expression of CDKN2A in melanoma cells led to potent growth inhibition and apoptosis, whereas knockdown of BRAF or expression of CDKN2A alone did not." (PMID 20140953, 2010). "However, CDKN1A and CDKN2A expression differences have not been found in different subtypes of melanoma, suggesting that CDKN1A and CDKN2A may become new type markers." (PMID 38070141, 2023).
glioma (425 papers, 2003 to 2026). A benign or malignant brain and spinal cord tumor that arises from glial cells (astrocytes, oligodendrocytes, ependymal cells). "For oligodendroglioma, LMC1 was associated with higher grade glioma morphology, CNS grade 3, alterations of the CDKN2A/B locus, and chromosomal aberrations in addition to 1p/19q-codeletion." (PMID 40849395, 2025). "In conclusion, this retrospective study provides valuable insights into the prevalence and prognostic impact of BRAF V600E mutation and CDKN2A deletion in pediatric high-grade glioma." (PMID 40860828, 2025). "The mechanisms by which hemizygous CDKN2A/B loss and focal amplifications impact tumor behavior continue to be investigated across gliomas and other cancer subtypes." (PMID 39584448, 2025). "Aggressive subsets within wild-type gliomas were further defined by CDKN2A/B deletion (26.9%) and NF1 mutation (7.8%)." (PMID 41377022, 2025). "Decreased CDKN2A expression is a marker of poor prognosis in high-grade gliomas, while poor prognosis in ovarian and bladder cancers is associated with increased CDKN2A expression." (PMID 39253931, 2025). "Preliminary results regarding 1p/19q codeleted PGOs and CDKN2A/B loss PGOs identification endorse testing in a prospective intraoperative glioma patient cohort." (PMID 39578301, 2025). "Among IDH-mut gliomas the presence of homozygous cyclin-dependent kinase inhibitor 2 A/B (CDKN2A/B) gene deletions of the chromosome 9p21 are associated with significantly poorer prognosis." (PMID 39593128, 2024). "Cyclin-dependent kinase inhibitor A/B (CDKN2A/B) is a tumor suppressor gene in chromosome 9p, which was noted to be deleted in gliomas before the IDH mutation was discovered." (PMID 38473369, 2024). "Progression-free survival (PFS) and overall survival (OS) are significantly shorter in patients with IDH-mutated low-grade gliomas with homozygous deletion of CDKN2A." (PMID 39457569, 2024). "We found that CDKN2A homozygous deletion strongly affected the prognosis of WHO grade 4 glioma patients with IDH mutation as well as the IDH wildtype." (PMID 39457569, 2024). "In patients with IDH-mutated astrocytomas, the presence of CDKN2A/B homozygous deletion leads to clinical behavior consistent with that of CNS WHO grade 4 gliomas." (PMID 39457569, 2024). "The status of CDKN2A/CDKN2B homozygous deletion linked to the INTS9 expression was found only in the IDH mutant glioma, including IDH mutant astrocytoma and oligodendroglia." (PMID 37537630, 2023). "In histologically lower grade gliomas, CDKN2A homozygous deletion is associated with more aggressive clinical course and is a molecular marker of grade 4 status in the 2021 WHO diagnostic system." (PMID 37138345, 2023). "Regarding to the development molecular based glioma classification, WHO CNS5 has therefore included molecular diagnostic criteria such as IDH mutation CDKN2A/B homozygous deletion for the classification of infiltrating gliomas." (PMID 36720864, 2023). "Among brain tumors, CDKN2A loss has greatest clinical implications in histologically low and intermediate grade gliomas and meningiomas." (PMID 37138345, 2023). "Nanopore sequencing has occasionally been used to study gliomas, one example being the detection of mutations of the gene for the “cyclin-dependent kinase inhibitor 2A/B (CDKN2A/B) in IDH-mutated gliomas." (PMID 38275375, 2023). "Early cytogenetic studies identified recurrent loss of the short arm of chromosome 9 in glioma cell lines, many involving the 9p21 locus, which includes CDKN2A and CDKN2B." (PMID 37504251, 2023). "We also observed regional heterogeneity in genes associated with poor clinical prognosis in IDH-mutant glioma, including CDKN2A/B, CDK4, MYC, MYCN, and PDGFRA23." (PMID 37770427, 2023).